MC4R (melanocortin 4 receptor)
Diseases named in the same sentence as MC4R in open-access papers (continued):
Sharing a sentence is not in itself a finding about the gene and the disease.
Obesity (continued). "Therefore, MC4R variants interacted with energy intake and mental stress levels to promote obesity." (PMID 27213003, 2016). "The lack of significant changes in neuropeptide expression in the hypothalamus of Mc4rR41X/+ mice, other than the change in Avp mRNA level, implies that MC4R haploinsufficiency may cause obesity through mild effects at the multiple sites or in a transcription-independent manner." (PMID 27585985, 2016). "However, the relative contribution of common variation in/near MC4R to risk of obesity in this population was largely unknown." (PMID 25103139, 2014). "Although the effect size of common variation in MC4R is smaller than that of the rare coding variants, because of the greater frequency/prevalence within the population, the common SNPs are likely to have a greater overall impact on obesity predisposition at the population level." (PMID 25103139, 2014). "More common, but still quite rare (minor allele frequency (MAF) <5% in most populations) MC4R non-synonymous SNPs (nsSNPs) (rs2229616/Val103Ile and rs52820871/Ile251Leu) have been reproducibly associated with a protective effect from severe and common forms of obesity." (PMID 24820477, 2014). "Thus, insulin-independent diabetes associated with obesity, which have perturbed leptin receptor and/or MC4R signaling, may be resistant to the DPP-4 inhibitor." (PMID 24804243, 2014). "We speculate that even modestly altered MC4R activity can influence obesity due to a long-term effect that can be exacerbated by environmental factors such as food choice and/or variants in other obesity related genes." (PMID 24705671, 2014). "In addition to rare variants which cause highly penetrant forms of monogenic obesity, common variants in MC4R have been associated with body mass index (BMI) in genome wide association scans suggesting that variation at this locus also contributes to obesity in the general population." (PMID 23404466, 2013). "Besides, studies support that the association of FTO rs9939609 and the MC4R rs17782313 polymorphisms with type-2 diabetes and obesity could be modulated and depended on diet." (PMID 23849767, 2013). "Whether silencing of E3 is able to increase surface expression and function of obesity-linked MC4R variants and whether modulation of the activity of E3 in vivo could protect against the obesity associated with mutations in MC4R are topics to be addressed in future studies." (PMID 23251400, 2012). "In addition, several mutations in ECL1 of the MC4R have been linked to obesity including a Thr-to-Met substitution (residue 112) which profoundly decreases the cell surface expression of the receptor and an insertion of an extra adenine resulting in loss of function." (PMID 21931793, 2011). "A careful investigation of MC4R has therefore invalidated the synthetic association hypothesis at this locus, and supports the concept of an independent contribution of both rare and common variants at the same locus for obesity risk." (PMID 22043165, 2011). "Consequently, the genomic region of Haplo 3 (201,708 base pairs) could be a focus of a deep sequencing approach aiming at the detection of additional obesity mutations/polymorphisms outside of the MC4R coding region." (PMID 21085626, 2010). "In addition, since THIQ is able to elicit a partial response from some mutated MC4Rs, our findings suggest that THIQ may be a potential obesity therapeutic for people carrying MC4R mutations." (PMID 17668051, 2007). "Thus, the question remains whether there are other forms of obesity with a marked genetic influence, such as that noted for MC4R mutation–linked obesity." (PMID 17196040, 2006). "Setmelanotide, an MC4R agonist, has demonstrated anti-obesity effects in genetic forms of obesity; however, its efficacy and mechanisms in HO remain unexplored." (PMID 41601974, 2026). "Large-scale research has also found positive associations between obesity and other gene mutations, such as MC3R and MC4R." (PMID 41596694, 2026).
Obesity (continued). "Obesity resulting from melanocortin-4 receptor (MC4R) dysfunction is characterized by combined metabolic dysregulation and maladaptive reward-related behaviors that limit the durability of existing therapies." (PMID 42196303, 2026). "Over the last several decades, the pharmaceutical industry pursued melanocortin-4 receptor-selective agonists for the treatment of general obesity." (PMID 41907544, 2026). "This contrasts with homozygous/bi-allelic carriers of LoF mutations in other genes in the leptin-melanocortin signalling pathway -LEP, LEPR, POMC, PCSK1 and MC4R-who almost inevitably develop severe obesity at an early age." (PMID 41386534, 2026). "Clinically, post-surgical hypothalamic injury patients often face weight regain triggered by overeat, and our results provide experimental evidence for targeting MC4R to prevent this complication—though its durability in human obesity requires validation." (PMID 41601974, 2026). "Mutations associated with monogenic obesity follow autosomal recessive (LEP, LEPR, POMC, and PCSK1) or autosomal dominant (MC4R, SH2B1, SIM1, GNAS) modes of inheritance." (PMID 41751424, 2026). "It provides potent anti-obesity effects with a favorable safety profile, in contrast to first-generation MC4R agonists that were limited by cardiovascular side effects." (PMID 41601974, 2026). "From a biological perspective, it reflects the transmission of obesity-susceptible genes (e.g. FTO, MC4R) that regulate energy homeostasis, appetite control, and adipocyte differentiation." (PMID 41543512, 2026). "Given this variability in treatment response, individualized therapeutic approaches should be considered for patients with MC4R-related obesity." (PMID 41489710, 2026). "Monogenic obesity, often characterized by early-onset and severe obesity, results from rare mutations in genes such as LEP (leptin), MC4R (melanocortin 4 receptor), and SH2B1 (SH2B adaptor protein 1)." (PMID 40004938, 2025). "Increasing data indicates that SNPs and rare mutations in genes such as FTO, MC4R, LEPR, and POMC influence not only the risk of obesity but also significantly impact weight loss, WR, and metabolic outcomes following bariatric surgery." (PMID 41226372, 2025). "For example, polymorphisms in the FTO, MC4R, LEP, and LEPR genes have been significantly associated with obesity and hypertriglyceridemia in Mexican children aged 4–13 years (n = 718)." (PMID 40647298, 2025). "Through genomic analysis, scientists have identified multiple genes associated with obesity, including the fat mass and obesity-associated gene (FTO), melanocortin 4 receptor gene (MC4R), and leptin gene (LEP)." (PMID 40871725, 2025). "We observed significant upregulation of FTO and downregulation of MC4R in the gastric tissue of patients with obesity, correlating with altered adiponectin levels and insulin resistance." (PMID 41423640, 2025). "Global knock out of MC4R in a mouse results in obesity and reduced chemosensitivity, implying the potential neuromediation of breathing through MC4R." (PMID 39542230, 2025). "The leptin-melanocortin pathway is the primary cause of monogenic obesity, and numerous genes, including AgRP, PYY (orexogenic) or MC4R, interfere with the appetite and weight regulation system." (PMID 40278960, 2025). "At the genetic level, the fat mass and obesity-associated gene (FTO) and the MC4R gene are among the most consistently linked with obesity through genome-wide association studies." (PMID 41423640, 2025). "Using disruption of MC4R brought about by CRISPR, obesity susceptibility and potential therapy targets have been studied in mice models." (PMID 40430848, 2025). "Shortening of MC4R-positive cilia in hypothalamic neurons disrupts the regulation of energy homeostasis, resulting in obesity." (PMID 40636449, 2025).
Obesity (continued). "In a Turkish study involving 105 children with early-onset obesity and analysis of 41 genes, approximately 10.5% of the variants were found in the SIM1, POMC, PCSK1, MC4R, and LEPR genes." (PMID 40149731, 2025). "A study in Italy that screened 209 patients with obesity for mutations in the MC4R, LEP, and LEPR genes identified only one novel pathogenic frameshift variant in the MC4R gene, which disrupted gene signaling." (PMID 40149731, 2025). "The most prevalent genes linked to monogenic obesity are leptin (LEP), leptin receptor (LEPR), and melanocortin 4 receptor (MC4R) genes." (PMID 40024983, 2025). "In relation to obesity, the FTO variants (rs9939609 and rs8050136) and MC4R variants (rs17782313 and rs2229616) have been widely recognized for their roles in regulating appetite and energy balance." (PMID 40944253, 2025). "Here we investigated the clinical response of men and women in the SURMOUNT-1 trial who carried pathogenic mutations in the melanocortin 4 receptor (MC4R) gene, the most common genetic cause of obesity." (PMID 40858971, 2025). "Obesity, the main risk factor for metabolic syndrome, is affected by genetic variations in leptin (LEP), leptin receptor (LEP), and melanocortin 4 receptor (MC4R)." (PMID 40430848, 2025). "Targeted hormone replacement therapy with the melanocortin-4 receptor agonist, setmelanotide, has been shown to be very effective in children with monogenetic obesity such as Bardet-Biedl syndrome." (PMID 40746184, 2025). "Faulty MC4R signalling in the dorsal raphe nucleus interferes with both feeding and anxious behaviour, creating a point that ties obesity and depression in mice models." (PMID 41375608, 2025). "The highest prevalence of monogenic obesity was observed in a Pakistani population, where 30% of children with obesity carried pathogenic variants in the LEP, LEPR, and MC4R genes." (PMID 40149731, 2025). "In this context, the patient's clinical response contributes to a growing body of literature on MC4R-targeted therapy for syndromic obesity and suggests potential immunomodulatory benefits." (PMID 41333852, 2025). "Rare MC4R pathway diseases of obesity include proopiomelanocortin, proprotein convertase subtilisin/kexin type 1, or leptin receptor deficiency, or Bardet-Biedl syndrome (BBS)." (PMID 40847358, 2025). "In conclusion, this study demonstrates altered expression of FTO and MC4R in the gastric tissue of patients with clinical obesity and suggests links with adipokine regulation and insulin resistance." (PMID 41423640, 2025). "Recent studies by Blaess and co-workers have shown that the MC4R pathway is disrupted in patients with the syndrome, leading to hyperphagia and, thus, obesity." (PMID 40718228, 2025). "Seven publications reported outcomes of MBS in patients with obesity caused by rare variants in LEPR, MC4R, NCOA1, PCSK1, POMC, SH2B1, or SIM1." (PMID 40560452, 2025). "Recent pharmacogenomic studies have further highlighted therapeutic opportunities for monogenic obesity, particularly through MC4R agonists and leptin replacement strategies." (PMID 41302083, 2025). "A unique role for the MC4-R in the control of energy balance is defined by the obesity syndrome that results from its absence, which is very similar to the Agouti disease." (PMID 41302083, 2025). "In line with a role for the leptin-melanocortin system in energy homeostasis, individuals with genetic defects in leptin signaling, POMC, or MC4R present with increased appetite and obesity." (PMID 41251447, 2025). "Numerous genes found by GWA scans, including MC4R (melanocortin-4 receptor) and FTO (fat mass and obesity-associated), have been firmly linked to the risk of Obesity in a variety of populations." (PMID 41302083, 2025). "Loss-of-function mutations in the POMC, MC4R, and MC3R genes cause severe obesity, lowering the length and quality of life of the patients due to complications such as cardiovascular disease, type 2 diabetes, and NAFLD." (PMID 40001512, 2025).
Obesity (continued). "Setmelanotide, a melanocortin-4 receptor agonist, is reserved for rare cases of genetically confirmed monogenic obesity." (PMID 41212412, 2025). "Specific mutations in genes that participate in the leptin-melanocortin pathway, such as those encoding leptin, leptin receptor (LepR), melanocortin-4 receptor (MC4R), and pro-opiomelanocortin (POMC), are recognized to cause monogenic forms of obesity." (PMID 41321496, 2025). "Further studies on cat samples from different countries and breeds would shed light on the relationship between this gene and obesity and will be useful in revealing the molecular role of MC4R protein in energy metabolism in cats." (PMID 40035963, 2025). "When compared to the increasingly common proopiomelanocortin (POMC) and leptin receptor (LEPR) gene mutations, melanocortin-4 receptor (MC4R) gene polymorphisms are seen to be linked to BED and obesity." (PMID 40077044, 2025). "Dolinov also found that the abnormal hypomethylation of the Avy gene in agouti mice leads to the decreased function of MC4R in the hypothalamus, thus resulting in obesity." (PMID 40868241, 2025). "Using these methods, we performed a DMS of the melanocortin-4 receptor (MC4R), a G-protein-coupled receptor (GPCR) implicated in obesity and an active target of drug development efforts." (PMID 40202051, 2025). "Rather than acting independently, environmental exposures, including diet quality, physical activity, socioeconomic conditions, and psychosocial stress, interact with genetic predispositions (e.g., FTO, MC4R, LEP) to modulate obesity risk." (PMID 41302083, 2025). "Increased food intake, reduced energy expenditure, and increased body fat were noted in mouse models of MC4R-related obesity." (PMID 40001512, 2025). "Previous studies have demonstrated that MC4R-related obesity can follow both autosomal dominant and recessive inheritance patterns." (PMID 40428329, 2025). "In studies conducted in adults, SNPs in the genes FTO, MC4R, TMEM18, TNNI3K, SEC16B, GNPDA2, and POMC are strongly associated with obesity risk." (PMID 40722558, 2025). "Kinetic assays performed on cells transfected with equal concentrations of MRAP2 and MC4R show impairment of cAMP and/or IP3 signaling by the obesity-associated variants." (PMID 41401256, 2025). "In patients with BBS, the MC4R pathway is impaired, which leads to hyperphagia and decreased energy expenditure, resulting in early‐onset severe obesity." (PMID 40186386, 2025). "Mutations in this gene are one of the most common causes of monogenic obesity, and together with the genes encoding leptin and LEPR, MC4R explains 30% of extreme obesity in children." (PMID 41150735, 2025). "MC4R knockout mice, widely used as a genetic model of obesity, exhibit multiple deficits in olfactory behaviors." (PMID 41262475, 2025). "One of the DMRs overlapped MC4R (OMIM *155541), which is associated with autosomal dominant and recessive obesity." (PMID 40044822, 2025). "Setmelanotide, a melanocortin-4-receptor (MC4R) agonist, is the first US Food and Drug Administration–approved therapy for obesity in ciliopathies such as BBS and AS." (PMID 41312179, 2025). "Monogenic obesity is caused by mutations predominantly in the leptin-melanocortin system, such as LEP, LEPR, POMC, and MC4R genes." (PMID 40636093, 2025). "Genetically, the Fat Mass and Obesity-Associated (FTO) gene and the Melanocortin-4 Receptor (MC4R) gene are recognized as contributors to polygenic and monogenic obesity, respectively." (PMID 41423640, 2025). "FTO expression was significantly upregulated in the obesity group (fold-change: 5.8 vs. 1.0; p < 0.001), while MC4R expression was markedly downregulated (fold-change: 0.1 vs. 1.0; p < 0.001)." (PMID 41423640, 2025). "As such, setmelanotide, an MC4R agonist, has been approved for use to target the obesity and hyperphagia experienced by patients with BBS." (PMID 41048439, 2025).
Obesity (continued). "We also compared weight gains in contemporaneously studied Mc4r+/− mice, the far less severely affected heterozygotes of the severe monogenetic obesity Mc4r−/− mouse." (PMID 39956805, 2025). "Across diverse ancestries, FTO and MC4R consistently emerge as the most replicated obesity loci, demonstrating cross-population robustness." (PMID 41302083, 2025). "Specifically, we have demonstrated that genetically ablating cilia or inhibiting cAMP production in the cilia of these MC4R neurons results in increased food intake and obesity." (PMID 39899600, 2025). "Genes implicated in monogenic obesity include POMC, LEP, LEPR, MC3R, and MC4R, while polygenic obesity involves variants in genes such as FTO, UCP1-3, MC4R, ADRB1-3, and SLC6A14." (PMID 41302083, 2025). "Loss of Gpr45 disrupted ciliary localization of Gαs, blunted local cAMP signaling, and impaired MC4R activation, leading to increased food intake and obesity." (PMID 41009961, 2025). "This includes SNPs in genes such as the fat mass and obesity-associated (FTO) (rs9939609), melanocortin 4 receptor (MC4R) (rs17782313), tumor necrosis factor-alpha (TNF) (rs1800629), and IL6 (rs1800795)." (PMID 40278374, 2025). "Nevertheless, its segregation pattern does not correspond with the previously outlined autosomal dominant or recessive inheritance models for MC4R-related obesity." (PMID 40428329, 2025). "The associated hyperphagia is a pathophysiological driver of severe obesity in patients with MC4R pathway diseases." (PMID 40528426, 2025). "Dysfunction of the MC4R pathway results in hyperphagia and reduced energy expenditure, contributing to early‐onset, severe obesity." (PMID 40528426, 2025). "Specific ablation of MC4R in ARCPOMC neurons also leads to obesity, decreased energy expenditure, and impaired insulin sensitivity." (PMID 39974186, 2025). "MC4R blockade induces obesity in rodents, e.g., in mice overexpressing a natural MC4R blocker, an agouti-related peptide (AgRP); MC4R-knockout mice also show an obesity phenotype." (PMID 40232848, 2025). "Specific genotype combinations of MC4R rs17782313 and SH2B1 rs7359397 (TC-CC and TC-CT) confer a substantially elevated obesity risk−15.58-fold higher than other genotypes—through synergistic regulation of the leptin–melanocortin pathway." (PMID 41340654, 2025). "Implementing next-generation sequencing (NGS) to identify variants in Lep, LepR, MC4R, and POMC genes enables timely, genetically guided interventions for non-syndromic early-onset obesity in children and adolescents." (PMID 40278960, 2025). "Ultimately, the therapeutic promise of MC4R agonists like setmelanotide underscores the potential of personalized medicine in treating genetically influenced obesity." (PMID 40428329, 2025). "Early-onset obesity in PHP1A is attributed to abnormal function of the melanocortin-4 receptor in the hypothalamus, an area affected by tissue specific imprinting." (PMID 40806967, 2025). "For example, variants of the fat mass and obesity-associated gene (FTO) and melanocortin 4 receptor (MC4R) genes have been shown to be associated with higher BMI and obesity measures, with urban living amplifying the effect of the FTO polymorphism." (PMID 40944253, 2025). "Another gene suspected of influencing the incidence of obesity and higher BMI is the melanocortin-4 receptor gene (MC4R)." (PMID 39458556, 2024). "Previous studies have established a significant association between several genes and obesity, such as the fat mass and obesity-associated (FTO) gene, melanocortin-4 receptor (MC4R) gene, and leptin receptor (LEPR) gene." (PMID 38674446, 2024). "Specifically, CLOCK/CC, FTO/AA, and LEP/AA genotypes were strongly associated with higher obesity metrics and emotional eating scores, while GHRL/TT and MC4R/CC were linked to increased BMI and WHR." (PMID 39203789, 2024).